RNU6-1080P (RNA, U6 small nuclear 1080, pseudogene)
Gene: Small nuclear RNA gene on chromosome 7 (73,339,094 to 73,339,200, reverse strand). Ensembl gene ENSG00000206709.
Homologues: Orthologues: chimpanzee U6 (99% identical), macaque U6 (92% identical), guinea pig U6 (68% identical), rabbit U6 (65% identical), pig U6 (64% identical), rabbit U6 (62% identical). Paralogues in human: RNU6-41P (88% identical), RNU6-44P (87% identical), RNU6-116P (86% identical), RNU6-12P (86% identical), RNU6-13P (86% identical), RNU6-166P (86% identical), RNU6-25P (86% identical), RNU6-26P (86% identical), RNU6-32P (86% identical), RNU6-378P (86% identical), RNU6-393P (86% identical), RNU6-589P (86% identical), and 1287 more.